EPIC1 (epigenetically induced MYC interacting lncRNA 1)
Diseases named in the same sentence as EPIC1 in open-access papers (continued):
Sharing a sentence is not in itself a finding about the gene and the disease.
cancer (14 papers, 2018 to 2025). A tumor composed of atypical neoplastic, often pleomorphic cells that invade other tissues. "Studies have reported that LncRNA EPIC1 promotes cell cycle progression by interacting with MYC through EPIC1’s 129–283 nt region in Cancer." (PMID 37639158, 2023). "Cancer cells with EPIC1 overexpression have a strong resistance to PD-1 blocking treatment; and knock-out of EPIC1 can reverse this resistance." (PMID 36384676, 2022). "The lncRNA EPIC1 has been shown to promote cell cycle progression in cancer cells through interaction with MYC." (PMID 33618674, 2021). "EPIC1 has been characterized as an oncogenic lncRNA in various types of human cancers." (PMID 32322669, 2020). "Cell viability, the CCK-8 OD, was increased in primary cancer cells with Lnc-EPIC1 overexpression." (PMID 33170148, 2020). "lncRNA EPIC1 has been reported to play a critical role in a wide range of human cancers." (PMID 32322669, 2020). "Moreover, 16 out of 18 EPIC1-correlated pathways in 505 cancer cell lines are significantly regulated by EPIC1-knockdown (FDR < 0.25, GSEA) (see Methods section)." (PMID 30093685, 2018). "The de-methylated lcnRNA gene EPIC1 can promote the cell propagation in cancer." (PMID 30419941, 2018). "MYC could interact with lncRNA EPIC1 to promote cell cycle progression in cancer." (PMID 40478912, 2025). "In our list, three lncRNAs, including EPIC1, SBF2-AS1 and DNM3OS, have RNA-seq data for wild-type (WT) and lncRNA knock-down (KD) from the corresponding cancer cell line models." (PMID 34315441, 2021). "The scramble control siRNA (“scr”) failed to alter Lnc-EPIC1 expression and cancer cell behaviors." (PMID 33170148, 2020). "EPIC1 has been found to promote the cell resistance to iBET762 (bromodomain and extra-terminal motif inhibitor) and JQ-1 via activation of MYC transcriptional activity in cancer cells, suggesting that EPIC1 could be useful as a predictive lncRNA for BET inhibitors." (PMID 32322669, 2020).
tumor (12 papers, 2020 to 2025). "Among these, we identified upregulation of several lncRNAs previously connected to tumor progression, including EPIC1, CASC9, and ZFPM2-AS1." (PMID 38493239, 2024). "Tumor tissue-specific lncRNA EPIC1 correlated with lower infiltration and activation of CD8+ T cells as well as decreased tumor antigen presentation in multiple cancers." (PMID 37346034, 2023). "In most investigated cell lines and tumor samples from various tumor entities, EPIC1 was overexpressed and correlated with poor prognosis and enhanced tumor cell proliferation." (PMID 32331331, 2020). "Furthermore, EPIC1 has been evidenced to block the presentation of tumor antigens in BC, thereby facilitating the immune escape of tumor cells and contributing to resistance against checkpoint inhibitor therapy in mouse models." (PMID 40149989, 2025). "As IFN-γ signaling is an integral part of anti-tumor immunity, these lncRNAs, in particular lncRNA EPIC1 due to its pan-cancer applicability, may represent a promising target for therapeutic intervention." (PMID 37346034, 2023). "Their analysis also found that tumor-specific lincRNAs, including EPIC1, may modulate tumor immune responses in multiple cancer types." (PMID 36810034, 2023). "Overexpression of EPIC1 leads to promotion of tumor growth in cell lines and mice." (PMID 32322669, 2020). "EPIC1 interacts with EZH2 and regulates the expression of IFNGR1, TAP1/2, ERAP1/2, and MHC-I, leading to an impaired presentation of tumor antigen." (PMID 38933287, 2023).
infection (3 papers, 2017 to 2026). The state of being infected such as from the introduction of a foreign agent such as serum, vaccine, antigenic substance or organism. "Both the cytoplasmic effector Pi04314 and an apoplastic effector, EPIC1, were secreted from haustoria, demonstrating the importance of these structures during infection." (PMID 28758684, 2017). "Here, we describe a study of secretion and delivery, during infection, of two effectors from P. infestans: the cytoplasmic effector Pi04314 and the apoplastic effector EPIC1." (PMID 28758684, 2017). "In addition to Pain1 and Pain2, P. infestans also secretes cystatin-like inhibitors EpiC1 and EpiC2B into the apoplast during infection." (PMID 41512033, 2026). "Using confocal microscopy, we investigated where the effectors Pi04314 and EPIC1 are secreted during infection, and whether detection of the former can be observed in the host nucleus, its site of action." (PMID 28758684, 2017). "Using brefeldin A (BFA), a well‐characterized inhibitor of Golgi‐mediated secretion that has been used to study M. oryzae effector secretion, we investigated whether Pi04314 and EPIC1 are conventionally secreted by the pathogen during infection." (PMID 28758684, 2017). "EPIC1 and EPIC2B were found to bind and inhibit PIP1 and RCR3, two tomato defense papain-like cysteine proteases in the apoplast during infection." (PMID 28459807, 2017).
EPIC1 also shares sentences with these, for which no sentence is quoted: gallbladder cancer (1 paper); glioblastoma (1).